OR56B1 (olfactory receptor family 56 subfamily B member 1)
Description:
Odorant receptor.
Synonyms: OR56B1P; OR11-65
Tractability: Antibody: UniProt places it where antibodies can reach, with medium confidence; UniProt predicts a signal peptide or a membrane-spanning region; its Gene Ontology location is reachable by antibodies, with medium confidence.
Gene: Protein-coding gene on chromosome 11 (5,736,448 to 5,738,523, forward strand). Ensembl gene ENSG00000181023.
Subcellular location: Cell membrane
Pathways (Reactome):
Sensory Perception: Expression and translocation of olfactory receptors
Gene Ontology:
Molecular function: olfactory receptor activity; G protein-coupled receptor activity; signaling receptor activity
Biological process: cellular response to lipid; detection of chemical stimulus involved in sensory perception of smell; G protein-coupled receptor signaling pathway; system process
Cellular component: plasma membrane; membrane
Genetic constraint (gnomAD): Loss-of-function variants: 14 observed, 13.14 expected, observed/expected ratio (o/e) 1.07, 90% interval 0.7 to 1.64. The upper end of that interval is the gene's LOEUF score, 1.64, which puts it in group 6 of 6, group 1 being the genes least tolerant of losing a copy. Missense variants: 434 observed, 400.78 expected, observed/expected ratio (o/e) 1.08, 90% interval 1 to 1.17. Synonymous variants: 158 observed, 152.05 expected, observed/expected ratio (o/e) 1.04, 90% interval 0.91 to 1.19.
Homologues: Orthologues: chimpanzee OR56B1 (98% identical), dog OR56B1 (83% identical), mouse Or56b1 (82% identical), guinea pig OR56B1 (80% identical), pig OR56B1 (80% identical), mouse Or56b1b (78% identical), tropical clawed frog or56c1 (41% identical). Paralogues in human: OR56B2 (70% identical), OR56B4 (64% identical), OR51L1 (40% identical), OR52E8 (40% identical), OR52K2 (40% identical), OR52K1 (39% identical), OR52L1 (39% identical), OR51A7 (39% identical), OR52E6 (39% identical), OR52J3 (39% identical), OR51E1 (38% identical), OR51G2 (38% identical), and 39 more.